CIB1 (calcium and integrin binding 1)
Diseases named in the same sentence as CIB1 in open-access papers (continued):
Sharing a sentence is not in itself a finding about the gene and the disease.
male infertility (1 paper, 2018). The inability of the male to effect fertilization of an ovum after a specified period of unprotected intercourse. "CIB1 is related to abnormal spermatogenesis, decreased testis weight and male infertility, while PCSK6 showed a role in female fertility (ovary cysts, increased ovary tumour incidence)." (PMID 29661130, 2018).
melanoma (1 paper, 2010). A malignant, usually aggressive tumor composed of atypical, neoplastic melanocytes. "Allografted melanoma tumors that developed in CIB1-KO mice were smaller in volume, had a distinct necrotic appearance, and had significantly less intra-tumoral microvessel density." (PMID 20804551, 2010).
metastasis (1 paper, 2021). The spread or migration of cancer cells from one part of the body (where they first appeared) to another. "This is further supported by the fact that the majority of mucinous tumors, which are associated with peritoneal carcinomatosis but not with liver metastasis have significantly lower CIB1 expression levels." (PMID 34794407, 2021).
mucinous tumors (1 paper, 2021). "Eleven mucinous tumors (29%) had high CIB1 expression levels compared to 67 non-mucinous tumors (50.8%) (p < 0.05)." (PMID 34794407, 2021).
neuroblastoma (1 paper, 2017). Neuroblastoma (NB) is the most common solid, extracranial childhood tumor. "In our initial experiments, we examined the effect of CIB1 on MPP+-induced apoptotic cell death in human neuroblastoma SH-SY5Y cells." (PMID 28939911, 2017).
nonsyndromic deafness (1 paper, 2017). An auditory system disease that is associated with permanent hearing loss caused by damage to structures in the inner ear and/or the middle ear, which is not associated with other signs and symptoms. "Among the family members, the Cib1 and Cib2 genes are expressed in mouse cochlear hair cells, and mutations in the human CIB2 gene have been associated with nonsyndromic deafness DFNB48 and syndromic deafness USH1J." (PMID 29255404, 2017).
pancreatic adenocarcinoma (1 paper, 2023). "The heatmaps showed that CIB1 is widely expressed in pancreatic adenocarcinoma cell lines, in which highly frequent KRAS mutation was also observed." (PMID 37187730, 2023). "The mRNA profiles in pancreatic adenocarcinoma cell lines were obtained to confirm the expression of CIB1." (PMID 37187730, 2023).
Parkinson disease (1 paper, 2017). A progressive degenerative disorder of the central nervous system characterized by loss of dopamine producing neurons in the substantia nigra and the presence of Lewy bodies in the substantia nigra and locus coeruleus. "To better understand the in vivo function of CIB1 in the pathogenesis of Parkinson’s disease, we examined the effect of CIB1 gene deletion on loss of dopaminergic neurons in the SNpc in a MPTP mouse model of the disease." (PMID 28939911, 2017). "Here, we show that CIB1 negatively regulates degeneration of dopaminergic neurons in a mouse model of Parkinson’s disease using 1-methyl-4-phenyl-1,2,3,6-tetrahydropyridine (MPTP)." (PMID 28939911, 2017). "In order to better understand a regulatory function of CIB1 in the pathogenesis of Parkinson’s disease, we have now investigated the inhibitory action of CIB1 against dopaminergic neurotoxicity in a mouse model of the disease using 1-methyl-4-phenyl-1,2,3,6-tetrahydropyridine (MPTP)." (PMID 28939911, 2017). "Given a guardian role of CIB1 in MPTP/MPP+-induced neurotoxicity, our findings may provide new insights into a potential therapeutic strategy for Parkinson’s disease." (PMID 28939911, 2017).
pulmonary fibrosis (1 paper, 2025). Chronic progressive interstitial lung disorder characterized by the replacement of the lung tissue by connective tissue, leading to progressive dyspnea, respiratory failure, or right heart failure. "In the mouse model of pulmonary fibrosis treated with bleomycin, the expression of CIB1 in lung tissue was elevated compared to that in the control group." (PMID 40076845, 2025). "CIB1 may synergistically regulate pulmonary fibrosis with ITGA11; however, further experimental validation is required." (PMID 40076845, 2025).
type 2 diabetes mellitus (1 paper, 2020). A type of diabetes mellitus that is characterized by insulin resistance or desensitization and increased blood glucose levels. "CIB1 is linked to the type II diabetes mellitus and leukocyte count GO terms." (PMID 33456716, 2020).
tumor (15 papers, 2010 to 2025). "The results of correlation tests revealed that CIB1 was associated with an immunosuppressive landscape with reduced anti-tumor cell infiltration." (PMID 37187730, 2023). "Subsequently, immunohistochemistry staining from the Human Protein Atlas (HPA) showed that high expression of CIB1 in tumor cells was associated with an increased tumor compartment and reduced stromal cellular abundance." (PMID 37187730, 2023). "Previous results have confirmed that high CIB1 expression was associated with a TME compressing of high tumor components but low stromal components." (PMID 37187730, 2023). "CIB1 was associated with increased tumor compartment and decreased stromal cell abundance, whereas low immune cell infiltration was associated with immunosuppression in the TME." (PMID 37187730, 2023). "The results all indicated that CIB1 was negatively associated with major anti-tumor contributors, notably, CD8+ T cells and high stromal cellular abundance was in favor of immune cell infiltrations." (PMID 37187730, 2023). "The results of immunohistochemistry staining demonstrated that high expression of CIB1 in tumor cells was associated with increased tumor compartments and reduced stromal cellular abundance." (PMID 37187730, 2023). "We believe that a better understanding of cell death mechanisms underlying tumor selectivity versus normal cells could provide further rationale to test a TRAIL-based combination treatment with CIB1 targeting." (PMID 30740034, 2019). "CIB1 plays an important role in promoting tumor cell cycle progression and proliferation, inhibiting tumor cell apoptosis, mediating tumor cell migration, and facilitating angiogenesis." (PMID 40076845, 2025). "In terms of the process of tumor cell apoptosis, CIB1 interacts with proteins such as DNA PKcs, TRF2, and EDD, participating in DNA damage repair and helping tumor cells resist apoptosis." (PMID 40076845, 2025). "In tumor cell migration, CIB1 enhances tumor cell migration and adhesion by interacting with various molecules such as PAK1 and FAK, thereby promoting tumor invasion and metastasis." (PMID 40076845, 2025). "After the suppression of CIB1 expression with siCIB1, the liver/tumor weight ratio was significantly lower than that in the corresponding oeUSP14 and oeNC groups." (PMID 38993552, 2024). "Immunohistochemical (IHC) staining was performed on PDX tumor samples to assess the influence of expression of CIB1 on the MAPK pathway." (PMID 38993552, 2024). "Interfering with CIB1 levels during host tumor progression in the presence of lenvatinib in both in situ liver tumor and PDX models and high CIB1 expression predict significantly poor postoperative survival in a neoadjuvant cohort." (PMID 38993552, 2024). "As CIB1 expression was proven to be associated with KRAS mutation and reprogrammed glucose metabolism, a comparison of CIB1 expression between tumor and normal tissues in TCGA cohort revealed that CIB1 was upregulated in PDAC." (PMID 37187730, 2023). "The results of quantitative analysis confirmed that high CIB1 expression was associated with fewer cells in stromal compartment and higher tumor components, compared with those with low CIB1 expression." (PMID 37187730, 2023). "Further, the ratio of stromal components and tumor components was significantly lower in samples with high CIB1 expression, indicating that high CIB1 expression led to an unbalanced tumor-stromal structure with high tumor components but low stromal components." (PMID 37187730, 2023). "Clinical characteristic demonstrated that overexpression of CIB1 is positive related to tumor metastatic." (PMID 33082516, 2021). "Regarding CRC, CIB1 induces tumor progression by promoting higher levels of vascular endothelial growth factor (VEGF) via Protein kinase D2 (PKD2) and thus is directly involved in angiogenesis." (PMID 34794407, 2021). "Adoptive transfer of macrophages transfected with CIB1‐siRNA localizes to the orthotopic MDA‐MB‐468 tumor." (PMID 31728272, 2019).
tumor (continued). "CIB1 depletion combined with docetaxel significantly enhanced tumor-specific cell death relative to each treatment alone." (PMID 30740034, 2019). "Taken together, our findings support a model in which CIB1 plays an important role in regulating tumor viability, growth, and angiogenesis." (PMID 20804551, 2010). "We report here that, in addition to regulating tumor growth, CIB1 in the host significantly contributes to tumor-induced angiogenesis." (PMID 20804551, 2010). "Although these data clearly demonstrate that CIB1 participates in ischemia-induced angiogenesis in vivo, its role in other forms of pathological angiogenesis, like tumor-induced angiogenesis is still unclear." (PMID 20804551, 2010). "In tumor cell proliferation and survival, CIB1 could regulate oncogenic signaling pathways such as PI3K/AKT and MEK/ERK." (PMID 40076845, 2025). "To validate the relationship between CIB1 expression, tumor and stromal components in real world, we then obtained IHC images of CIB1 from the HPA database to further assess the association between CIB1 expression and the cellular components of the TME in PDAC." (PMID 37187730, 2023). "Here, we hypothesized that CIB1 may be associated with metabolic reprogramming in PDAC and may thus affect the TME via modulating tumor and stromal cellular components and immune cells to establish an immunosuppressive TME." (PMID 37187730, 2023). "We further identified that CIB1 was positively correlated with the glycolysis, oxidative phosphorylation (Oxphos), and hypoxia pathways, as well as the cell cycle, which reflected increasing numbers of tumor cellular components in the TME." (PMID 37187730, 2023). "On the other hand, whether the knockdown of CIB1 would eventually boost the anti-tumor immunity was unknown." (PMID 37187730, 2023). "We divided the patients into two groups according to the expression level of CIB1 in tumor tissue." (PMID 33082516, 2021). "Moreover, patients with high CIB1 expression in tumor tissues had shorter overall survival and disease-free survival than patients with low CIB1 expression (P < 0.001)." (PMID 33082516, 2021). "CIB1 has been shown influenced many tumor cells activity via multiple signaling pathways." (PMID 33082516, 2021). "Pathogenic development of cib1 deletion strains is blocked immediately after plant penetration, resulting in the complete absence of tumour formation." (PMID 31802604, 2020). "To address the need to enhance tumor cell death and maintain tolerability by normal cells, we tested the targeting of CIB1 via RNA interference in combination with the commonly used chemotherapeutic agent, docetaxel, in both TNBC and a normal breast epithelial cell line." (PMID 30740034, 2019). "In contrast, CIB1 depletion alone or in combination with docetaxel did not significantly increase cell death in normal breast epithelial ME16C cells, suggesting that CIB1 targeting may improve chemotherapeutic efficacy by tumor-selective killing." (PMID 30740034, 2019). "Hence the data herein establish a regulatory role for CIB1 in tumor growth and pathological tumor-induced angiogenesis." (PMID 20804551, 2010). "To test this conjecture we allografted CIB1-KO mice with murine tumor cells that endogenously expressed either very low levels (B16 melanoma tumor cells) or very high levels (Lewis lung carcinoma cells) of MMP-2, as previously demonstrated by zymography analysis." (PMID 20804551, 2010). "Since pathological angiogenesis is highly dependent on many of these same processes, we hypothesized that CIB1 may also regulate tumor-induced angiogenesis." (PMID 20804551, 2010). "Furthermore, upregulated cell cycle pathway was observed in PDAC with low immune infiltration levels, indicating that CIB1-related metabolism reprogramming was negatively associated with the infiltration of immune cells in PDAC and promoted the growth of tumor cells." (PMID 37187730, 2023).
tumor (continued). "Therefore, we asked whether CIB1 depletion further enhances tumor-specific killing when combined with either the commonly used chemotherapeutic, docetaxel, or the cell death-inducing ligand, TRAIL." (PMID 30740034, 2019). "Overexpression of CIB1 significantly alleviated the USP14 knockdown-induced inhibition of tumor growth and tumor weight." (PMID 38993552, 2024). "Elevated CIB1 expression combined with upregulated glycolysis, oxidative phosphorylation (Oxphos), hypoxia pathway activation, and cell cycle promoted PDAC tumor growth and increased tumor cellular com-ponents." (PMID 37187730, 2023). "CIB1 has also been confirmed to contribute to two common oncogenic pathways, PI3K/AKT and Ras/MEK/ERK, which are essential for tumor cell survival and proliferation." (PMID 37187730, 2023). "Studies have proved that overexpression of CIB1 can lead to abnormal activation of AKT, thereby promoting the development of tumor cells." (PMID 33082516, 2021). "By contrast, expression of cib1 under the control of PUMAG_03597 (FB1∆cib1 × FB2∆cib1∆UMAG_03597::cib1) was sufficient to trigger anthocyanin production and the formation of small tumours." (PMID 31802604, 2020). "In a mouse model, the absence of CIB1 significantly limits tumor growth and angiogenesis, indicating that CIB1 plays a critical role in tumor-induced angiogenesis." (PMID 40076845, 2025). "CIB1 can also interact with PAK1 to affect the downstream signaling pathways of related signaling pathways such as PI3K/Akt and Ras/RAF/MEK/ERK and regulate the growth and proliferation of TNBC tumor cells." (PMID 37691919, 2023). "Since our previous studies demonstrated that CIB1-KO mice have decreased growth factor-mediated angiogenesis, and CIB1-KO ECs have attenuated MMP-2 expression, we hypothesized that CIB1-KO mice may also have a defect in tumor-induced angiogenesis." (PMID 20804551, 2010). "However, when cib1 was expressed under the control of PUMAG_12184 (FB1∆cib1 × FB2∆cib1∆UMAG_12184::cib1), virulence was almost completely abolished and no tumours were formed, resembling the ∆cib1 phenotype." (PMID 31802604, 2020).
cancer (13 papers, 2017 to 2025). A tumor composed of atypical neoplastic, often pleomorphic cells that invade other tissues. "CIB1 has been found to promote cell survival, growth and proliferation in cancer by regulating at least two prominent growth and oncogenic pathways, PI3K/AKT and MEK/ERK." (PMID 37645935, 2023). "We expect it be a helpful probe to further exploit and validate CIB1 as a promising anti-cancer target." (PMID 37645935, 2023). "The IHC images of CIB1 in cancer samples suggested that samples with strongly stained CIB1 had fewer cells and were more fibrotic compared to CIB1-negative samples, indicating that high expression of CIB1 was related to low stromal abundance." (PMID 37187730, 2023). "In addition, CIB1 interacts with telomerase reverse transcriptase (hTERT) to promote telomere activity and prolong telomeres, thereby maintaining the proliferation ability of cancer cells." (PMID 40076845, 2025). "Hence, we speculate that CIB1 as a target may provide new avenues for formulating effective combination therapies not only for TNBC but other cancers as well." (PMID 30740034, 2019). "Here, we applied optogenetic controlled PI3K module (named ‘Opto-PI3K’), which based on CRY2 and the N-terminal of CIB1 (CIBN), to rapidly and reversibly control the endogenous PI3K activity in cancer cells with light." (PMID 30237527, 2018). "FRASE-based virtual screening identifies a small-molecule CIB1 ligand (with binding confirmed in a TR-FRET assay) showing specific cell-killing activity in CIB1-dependent cancer cells, but not in CIB1-depletion-insensitive cells." (PMID 38956119, 2024). "By stabilizing CIB1 through deubiquitination, which facilitates the MAPK signaling cascade, USP14 enables sustained signaling despite the presence of lenvatinib, ultimately promoting cancer cell survival and proliferation." (PMID 38993552, 2024). "Therefore, knockout of CIB1 or over-expression of CIB2 will result in sphingosine accumulation and contribute significantly to cancer treatment by several approaches." (PMID 33123153, 2020). "Combination therapies involving CIB1 targeting could therefore provide safe and durable strategies for treatment of TNBC and potentially other cancers." (PMID 30740034, 2019). "Therefore, combination therapies that target CIB1 could prove to be a safe and durable strategy for treatment of TNBC and potentially other cancers." (PMID 30740034, 2019).